TRPC1 (transient receptor potential cation channel subfamily C member 1)
Description:
Forms a receptor-activated non-selective calcium permeant cation channel. Forms a heteromeric ion channel with TRPC4 or TRPC5 that has reduced calcium permeability compared to the homomeric TRPC4 or TRPC5 channel. Also permeable to monovalent ions including sodium, lithium and cesium ions. [Isoform Short]: Forms a receptor-activated non-selective calcium permeant cation channel. Also activated by intracellular calcium store depletion.
Synonyms: TRP1; HTRP-1
Tractability: Small molecule: a structure with a bound ligand is known; a high-quality ligand is known; it belongs to a druggable protein family. Antibody: UniProt places it where antibodies can reach, with high confidence; its Gene Ontology location is reachable by antibodies, with high confidence; UniProt predicts a signal peptide or a membrane-spanning region. PROTAC: a small molecule that binds it is known.
Gene: Protein-coding gene on chromosome 3 (142,724,034 to 142,807,888, forward strand). Ensembl gene ENSG00000144935.
Subcellular location: Cell membrane
Subcellular location (Human Protein Atlas): Vesicles
Pathways (Reactome):
Developmental Biology: Role of second messengers in netrin-1 signaling
Immune System: Antigen activates B Cell Receptor (BCR) leading to generation of second messengers
Muscle contraction: Ion homeostasis
Transport of small molecules: TRP channels
Gene Ontology:
Molecular function: ATPase binding; inositol 1,4,5 trisphosphate binding; monoatomic cation channel activity; protein binding; signaling receptor binding; store-operated calcium channel activity; calcium channel activity; calcium ion transmembrane transporter activity
Biological process: calcium ion transmembrane transport; melanin biosynthetic process; positive regulation of release of sequestered calcium ion into cytosol; regulation of cytosolic calcium ion concentration; response to calcium ion; calcium ion transport; regulation of cardiac conduction
Cellular component: cation channel complex; plasma membrane; receptor complex; membrane
Genetic constraint (gnomAD): Loss-of-function variants: 38 observed, 78.4 expected, observed/expected ratio (o/e) 0.48, 90% interval 0.37 to 0.63. The upper end of that interval is the gene's LOEUF score, 0.63, which puts it in group 2 of 6, group 1 being the genes least tolerant of losing a copy. Missense variants: 694 observed, 962.5 expected, observed/expected ratio (o/e) 0.72, 90% interval 0.68 to 0.77. Synonymous variants: 284 observed, 341.26 expected, observed/expected ratio (o/e) 0.83, 90% interval 0.75 to 0.92.
Homologues: Orthologues: chimpanzee TRPC1 (99% identical), macaque TRPC1 (99% identical), dog TRPC1 (99% identical), mouse Trpc1 (99% identical), pig TRPC1 (99% identical), rabbit TRPC1 (99% identical), guinea pig TRPC1 (99% identical), rat Trpc1 (99% identical), tropical clawed frog trpc1 (90% identical), zebrafish trpc1 (83% identical), Drosophila melanogaster Trpgamma (38% identical), Caenorhabditis elegans trp-2 (37% identical), and 2 more. Paralogues in human: TRPC4 (46% identical), TRPC5 (46% identical), TRPC6 (35% identical), TRPC7 (34% identical), TRPC3 (34% identical).
Diseases named in the same sentence as TRPC1 in open-access papers:
TRPC1 is named in the same sentence as 156 diseases in open-access papers, as found by Europe PMC text mining. Sharing a sentence is not in itself a finding about the gene and the disease. The quoted sentences say what the papers report.
breast carcinoma (46 papers, 2009 to 2025). "TRPC1 has been implicated in breast cancer cell proliferation, whereas TRPC6, TRPM7, and TRPV6 have demonstrated their involvement in the regulation of breast cancer cell proliferation and migration." (PMID 39334351, 2024). "In another study, the upregulation of Orai3 together with TRPC1 in breast cancer has been linked to HIF-1α, as its silencing reduced the expression of both channels." (PMID 36612099, 2022). "The upregulation of TRPC1 expression in breast cancer tissues and cells is associated with breast cancer metastasis." (PMID 35813831, 2022). "Another study finds that TRPC1 is positively related to the clinical stage and serves as an independent risk factor for metastasis in breast cancer patients." (PMID 35754147, 2022). "In vitro studies have revealed that TRPC1 expression is up-regulated during hypoxia-associated EMT in breast cancer cells." (PMID 30558192, 2018). "In MDA-MB-468 breast cancer cells, silencing of TRPC1 was associated with a marked reduction in constitutive ERK1/2 activity." (PMID 22666335, 2012). "Consequently, TRPC1 overexpression is associated with more aggressive breast cancer subtypes and poorer patient outcomes." (PMID 36158191, 2022). "Elevations of TRPC1 expression are common in breast cancer and may serve to predispose pre-neoplastic cells towards EMT by conferring a more proliferative and invasive phenotype." (PMID 35141145, 2021). "There are few studies on TRPC channels and breast cancer, but those that have been reported have targeted TRPC1 and TRPC3 as channels associated with breast cancer proliferation." (PMID 40078961, 2025). "The role of TRPC1 for the proliferative aspect of breast cancer can be summarised as downregulation of TRPC1 expression reduces the rate of cellular proliferation." (PMID 40078961, 2025). "TRPC1 is also highly expressed in breast cancer, and TRPC1 overexpression inhibits the proliferation and migration of ER-positive breast cancers." (PMID 40078961, 2025). "Knockdown of TRPC1 in MDA-MB-468 breast cancer cells attenuates unstimulated Ca2+ influx via ORAl1 in a Ca2+ influx-dependent manner, reduces cell proliferation rates and is associated with a decrease in S-phase cells." (PMID 40078961, 2025). "Breast cancer severity was previously shown to be correlated with TRPC1 channel expression that conferred upon it enhanced vulnerability to pulsed electromagnetic field (PEMF) therapy." (PMID 39594815, 2024). "TRPC1 expression is hence predictive of sensitivity to DOX, whereas chemoresistance is associated with downregulation of TRPC1 in breast cancer and ovarian cancer." (PMID 39594815, 2024). "Breast cancer cells exist in a state of sustained stemness and hence retain aberrantly elevated TRPC1 expression throughout most of the course of the disease." (PMID 39594815, 2024). "A magnetically induced TRPC1-mitochondrial signaling axis was previously demonstrated in normal and breast cancer cells and has potential for clinical exploitation." (PMID 39594815, 2024). "TRPC1 expression also positively correlates with the proliferative capacity of human breast cancer cells." (PMID 39594815, 2024). "Heightened TRPC1 expression was correlated with more advanced breast cancer grades as well as with greater doxorubicin uptake." (PMID 39594815, 2024). "Overexpression of TRPC1 inhibits proliferation and migration of ER+ breast cancer, and provides better prognosis by inhibiting the activation of PI3K/AKT pathway." (PMID 38706904, 2024). "Here, we show that a brief magnetic field exposure enhances DOX uptake in correlation with TRPC1 expression, rendering breast cancer-specific cytotoxicity." (PMID 39594815, 2024). "Breast cancer is hence developmentally poised for preferential vulnerability to this magnetic therapeutic strategy that targets TRPC1 expression." (PMID 39594815, 2024). "Given the fundamental role of TRPC1 in cell proliferation, TRPC1 represents a promising prognostic marker for breast cancer." (PMID 39594815, 2024).
breast carcinoma (continued). "The expression of the transient receptor potential canonical 1 (TRPC1) cation channel subunit correlates with breast cancer progression." (PMID 39594815, 2024). "TRPC1 silencing leads to reduction of Ca2+ signal mediated breast cancer process induced by FGFR1 activation." (PMID 38706904, 2024). "Pulsed electromagnetic fields (PEMFs) have been shown to activate TRPC1-mediated Ca2+ entry and downstream catalytic responses in healthy and breast cancer cells." (PMID 39594815, 2024). "The activation of AKT depends on Ca2+ through TRPC1 in lung cancer and hepatocellular carcinoma cell lines, and the activation of ERK1/2 depends on Ca2+ through TRPC1 in thyroid and different breast cancer cell lines." (PMID 36230869, 2022). "For instance, one previous study shows that TRPC1 expression in breast cancer tissues is higher than that in normal breast tissues." (PMID 35754147, 2022). "In MDA-MB-468 breast cancer cells, TRPC1 is involved in the transactivation of the epidermal growth factor receptor (EGFR) during hypoxia, leading to the increase in LC3B autophagy marker." (PMID 35806388, 2022). "It is illustrated that TRPC1 overexpression is linked with larger tumor size, the occurrence of lymph node metastasis and elevated TNM stage in breast cancer patients." (PMID 35106847, 2022). "Whereas in other studies, TRPC1 downregulation drives proliferation and growth in esophageal and breast cancer." (PMID 35887266, 2022). "Detailly, TRPC1 is upregulated in breast cancer tissue and is correlated with advanced clinicopathological features as well as poor prognosis in breast cancer patients." (PMID 35106847, 2022). "TRPC1 mediates hypoxia responses also in breast cancer cells, where HIF-1α promoted its upregulation." (PMID 35806388, 2022). "Clinically, TRPC1 is regarded as a biomarker for the prognosis of cancer patients, such as breast cancer and esophageal squamous cell carcinoma (ESCC)." (PMID 35548183, 2022). "Another study reveals that TRPC1 can serve as a prognostic biomarker in patients with breast cancer." (PMID 35548183, 2022). "In this context, a synthetic peptide based on PLC-γ1 SH2 domains, found to interact with TRPC1, revealed an anti-tumoral activity in breast cancer." (PMID 35565390, 2022). "For instance, in the PTEN deficient breast cancer cell line MDA-MB-468, TRPC1 silencing reduced the phosphorylation of AKT even though it slightly increased SOCE levels." (PMID 35887266, 2022). "Previous studies also investigate the prognostic value of TRPC1 in a series of solid carcinomas: TRPC1 is correlated with poorer prognosis in patients with breast cancer, colorectal cancer, and gastric cancer." (PMID 35106847, 2022). "Both studies further demonstrated reductions in breast cancer cell invasiveness in response to activation of either TRPC1 (PEMF exposure) or TRPC6 (Furin inhibition)." (PMID 35141145, 2021). "The sum of these data provide evidence for TRPC1 involvement in breast cancer metastatic reprogramming." (PMID 35141145, 2021). "Studies conducted in breast cancer tissue revealed that the claudin-low breast cancer subtype exhibited the highest TRPC1 expression levels compared to other subtypes." (PMID 34936030, 2021). "Increased TRPC1 expression has been reported to contribute to pancreatic cancer cell motility, breast cancer, non-small cell lung cancer, colon cancer, and glioblastoma multiforme proliferation and migration." (PMID 34199280, 2021). "Diverse TRP channel classes have been broadly implicated in the development of various cancers in particular, TRPC1 in the realm of breast cancer." (PMID 35141145, 2021). "Accordingly, Azimi and colleagues reported increased TRPC1 expression after hypoxia-induced EMT via HIF-1α signaling in breast cancer cells." (PMID 34360952, 2021). "TRPC1—TGFβ-induced EMT was shown to be mediated by store operated calcium entry (SOCE) involving STIM1 and TRPC1 in breast cancer cells." (PMID 34360952, 2021).
breast carcinoma (continued). "The capacity of PEMF-based therapies to mitigate proliferation and invasiveness of breast cancer cells by selectively targeting cells with high TRPC1 channel expression thus merits future investigation in human clinical trials." (PMID 35141145, 2021). "In breast cancer, our previous research also found that TRPC1 inhibited the proliferation, migration, and invasion of cancer cells." (PMID 33854967, 2021). "While the chemotherapeutic agents, cisplatin and carboplatin, are capable of downregulating TRPC1 channel expression in ovarian cancer cell lines, the effect of DOX on TRPC1 channel expression in breast cancer is unexplored." (PMID 35141145, 2021). "In breast cancers, TRPC1 and TRPC6 are found to be highly expressed in human breast ductal adenocarcinoma compared to the adjacent non-tumor tissues, indicating the potential roles of these two TRPCs in modulation of breast tumor progression." (PMID 32211326, 2020). "The claudin-low breast cancer subtype exhibited the highest TRPC1 expression levels compared to other subtypes." (PMID 32046188, 2020). "TRPC1 was reported to play an important role in basal-like breast cancer cell migrations with regulation of the epithelial to mesenchymal transition (EMT) procedure." (PMID 31003514, 2019). "Corresponding results were found in breast cancer cells, in which hypoxia increases TRPC1 expression and TRPC1 regulates hypoxia-induced signaling." (PMID 29772843, 2018). "In an effort to translate cell line experiment data to an in vivo patient situation, we analyzed KCa3.1 and TRPC1 mRNA expression in public breast cancer patient sample sets." (PMID 27183905, 2016). "We further studied the expression/localization of TRPC1 channels in human control (normal) and breast cancer tissue samples." (PMID 27793015, 2016). "The previous results clearly show the importance of KCa3.1 and TRPC1 function for MCF-7 breast cancer cell proliferation." (PMID 27183905, 2016). "In the MCF-7 breast cancer cell line, we previously demonstrated that TRPC1 provides a Ca2+ entry that regulates cell proliferation via ERK1/2 phosphorylation." (PMID 27183905, 2016). "Both KCa3.1 and TRPC1 have separately been described as involved in breast cancer cell proliferation." (PMID 27183905, 2016). "TRPC1 and TRPC6 have convincingly linked to SOCE in a growing number of human tumours, including breast carcinoma, glioblastoma multiforme (GBM), and hepatoma." (PMID 25126575, 2014). "The potential roles for specific Ca2+ channels in these pathways were assessed by siRNA-mediated silencing of ORAI1 and transient receptor potential canonical type 1 (TRPC1) channels in MDA-MB-468 breast cancer cells." (PMID 22666335, 2012). "As ORAI1 and TRPC1 regulate ERK1/2 activity in other cell types we assessed constitutive ERK1/2 phosphorylation in MDA-MB-468 breast cancer cells with ORAI1 or TRPC1 silencing." (PMID 22666335, 2012). "MDA-MB-468 breast cancer cells with TRPC1 silencing showed reduced cell number and the percentage of cells in the S-phase of the cell cycle." (PMID 22666335, 2012). "Interestingly, TRPC1 expression levels were completely different in different breast cancer cell lines." (PMID 40078961, 2025). "In contrast, the role of TRPC1 in breast cancer metastasis is inconsistent with TRPC2." (PMID 40078961, 2025). "TRPC1 expression has also been shown to predict sensitivity to DOX in breast cancer cells." (PMID 39594815, 2024). "Studies have shown that TRPC1 is highly expressed in breast cancer and may serve a protective role in limiting the proliferation and migration of breast cancer cells." (PMID 39682767, 2024). "Moreover, TRPC1 expression showed correlation with Ki-67 expression, a marker for cell proliferation and cancer staging in breast cancers." (PMID 39594815, 2024). "TRPC1 expression may thus serve as prognostic for breast cancer given its strong correlation to tumor progression, metastasis and EMT." (PMID 39594815, 2024).
breast carcinoma (continued). "Interestingly, PI3K modifies the channel activity of other members of the TRP family, such as TRPV1 in endothelial cells and neurons and TRPC1 in breast cancer cells." (PMID 38564162, 2024). "Additionally, TRPC1 knockdown in breast cancer cells reduces ERK1/2 phosphorylation and cell cycle progression." (PMID 36158191, 2022). "For instance, TRPC1 is upregulated in breast cancer cell lines and colorectal cancer cell lines." (PMID 35887266, 2022). "Previous studies suggested that AKT pathways may be regulated by TRPC1 and our previous work revealed that TRPC1 plays an essential role in the inhibition of breast cancer progression by inhibiting the PI3K/AKT signaling pathway." (PMID 33854967, 2021). "Additionally, it was also demonstrated that the claudin-low breast cancer subtype exhibited the highest TRPC1 expression levels compared to other subtypes." (PMID 34360952, 2021). "TRPC1 levels in breast cancer were dependent on HIF-1α following hypoxia-induced EMT." (PMID 32046188, 2020). "Indeed, TRPC1 is expressed highly in basal breast cancer cell lines and tumor tissues from patients suffering basal breast cancers, especially those accompanied with lymph node metastasis." (PMID 32211326, 2020). "Importantly, increased TRPC1 expression correlated with expression and increased proliferative and invasive capacity of small grade I breast cancer tumors." (PMID 32046188, 2020). "Specific remodeling of TRPC1 expression is also a feature of breast cancer cells." (PMID 30558192, 2018). "In addition, both KCa3.1 and TRPC1 mRNA and protein levels were shown to be higher in breast cancer tissue than in matched normal breast tissue." (PMID 27183905, 2016). "In addition, MCF-7 breast cancer cells accumulated in the G1 phase upon the KD of TRPC1, which was also found in the thyroid cancer cell line ML-1, where the expression of the CDK6, Cyclin D2, and D3 decreased, and the expression of their regulating inhibitor p21 increased." (PMID 35887266, 2022). "However, the dysregulated expression of TRPC1 will remain controversial and seems to be cell type-specific, as the upregulation of TRPC1 appears to have a protective role in prostate and some breast cancer patients." (PMID 35887266, 2022). "Therefore, chronic DOX exposure at the predetermined IC50 of native MCF-7 cells is capable of selecting against breast cancer cells with innately elevated TRPC1 expression to produce cellular progeny elaborating depressed TRPC1 expression, proliferative capacity and chemosensitivity." (PMID 35141145, 2021). "Furthermore, given previous evidence demonstrating that PEMF exposure modulates TRPC1 function, we examined whether TRPC1 expression level predicts breast cancer vulnerability to DOX and PEMF treatments." (PMID 35141145, 2021). "Many studies have demonstrated that the TRPC1 channel plays an important role in tumor cell proliferation, differentiation, apoptosis, migration, and invasion in distinct kinds of tumors, including breast cancer, prostate cancer, gastric cancer, and liver cancer." (PMID 33854967, 2021). "Also, TRPC1 was found to regulate positively pAkt in PTEN deficient breast cancer cell lines and the lack of TRPC1 or the inhibition of calcium entry reduces Akt phosphorylation and delays muscle cell differentiation." (PMID 32350291, 2020). "While TRPC1 is ubiquitously expressed in most tissues, its dysregulated activity may contribute to the hallmarks of various types of cancers, including breast cancer, pancreatic cancer, glioblastoma multiforme, lung cancer, hepatic cancer, multiple myeloma, and thyroid cancer." (PMID 32046188, 2020). "Also, no public knowledge exists on a role in the various molecular subtypes for breast cancer, or on the molecular mechanisms by which KCa3.1 and TRPC1 could be involved in breast cancer progression." (PMID 27183905, 2016).